FGFR4 (fibroblast growth factor receptor 4)
Diseases named in the same sentence as FGFR4 in open-access papers (continued):
Sharing a sentence is not in itself a finding about the gene and the disease.
cancer (continued). "Unfortunately, the association between the FGFR4 gene rs351855 G>A polymorphism and cancer risk remains controversial." (PMID 28445975, 2017). "In conclusion, our study demonstrates the association between the FGFR4 rs351855 G>A polymorphism and overall cancer risk." (PMID 28445975, 2017). "There is considerable evidence underlining the relationship between FGFR4 mutation and carcinogens and studies has been attempted to focus possible correlation between FGFR4 (G388R) mutation and different cancers in the local population." (PMID 27051190, 2016). "Most of the reports regarding FGFR4 and cancers have focused mainly on a common single-nucleotide polymorphism (SNP), FGFR4 Gly388Arg, of which at least one copy is present in approximately 30– 50% of the population." (PMID 27192118, 2016). "Unlike FGFR1-3, whose activating mutation plays a central role in tumorigenesis, FGFR4 is rarely mutated in cancer or in other diseases." (PMID 27192118, 2016). "FGFR4 somatic mutations are infrequent in cancer; Arg388 is the most common single nucleotide polymorphism (SNP) in FGFR4, which provokes enhanced stability and prolonged activation of the receptor." (PMID 23696849, 2013). "Previous studies reported associations between genetic variants in the FGFR2 and FGFR4 genes and development of various cancers." (PMID 19500394, 2009). "The Gly388Arg polymorphism in the fibroblast growth factor receptor 4 (FGFR4) gene has been reported to influence prognosis in a wide variety of cancer types." (PMID 17519899, 2007). "A positive correlation between the presence of the FGFR4 Arg388 allele and prognostic parameters as well as survival time was reported in variant cancer studies, including breast, colon, lung, prostate, head and neck cancers and high-grade soft-tissue sarcoma." (PMID 17088904, 2006). "A single nucleotide polymorphism in the gene for FGFR4 (−Arg388) has been associated with progression in various types of human cancer." (PMID 16721364, 2006). "FGFR4 p.G388R is also a common germline single-nucleotide polymorphism that replaces glycine with arginine in the transmembrane region; numerous studies and meta-analyses associate it with increased risk/poor prognosis in various cancers." (PMID 41517303, 2025). "There are multiple mechanisms that converge on FGFR4 regulation, and in addition to the direct induction caused by H. pylori protein acting on cancer epithelial cells, we have now revealed a regulatory network supported by both FGF19, the natural ligand of FGFR4, and by LIF/LIFR." (PMID 37945798, 2024). "As a result, FGFR4 inhibition for cancer therapy may be successful in treating cancer patients with FGFR4 high expression tumors, causing only minimal side effects." (PMID 36147913, 2022). "In the case of Filgotinib (BLU554), which is closely related to BLU9931, FGFR4 V550L mutations caused resistance to the drug in a clinical trial for hepatic cancer, clearly implicating FGFR4 as a driver of this cancer and V550L mutations as gate-keepers for the drug." (PMID 36097178, 2022). "Therefore, the prognostic impact of the FGFR4 Gly388Arg polymorphism in cancer patients still remains controversial." (PMID 34737965, 2021). "The FGFR4 overexpression is associated with metastasis and the late stages of cancer." (PMID 34026732, 2021). "Recently, an explosion of investigations has revealed the associations of FGFR4 gene polymorphisms with the risk, prognosis, or treatment outcome of numerous cancer types, such as head and neck, lung, prostate, breast, colon, ovarian, liver, and uterine cervical cancer." (PMID 34071523, 2021). "Beside the FGFR4 rs351855 G>A polymorphism, there are also other SNPs or mutations of FGFR4 which may affect the risk of cancer development or prognosis of cancer patients." (PMID 34737965, 2021). "Higher FGFR4 expression in RMS has been associated with advanced-stage cancer and poor survival." (PMID 33916788, 2021).
cancer (continued). "Moreover, it is known that under oxidative stress associated with inflammatory processes, FGFR4 can regulate cancer cell survival via mitogen-activated protein kinase (MAPK) and phosphoinositide 3-kinase/protein kinase B (PI3K/AKT) signaling pathways." (PMID 34200439, 2021). "To comprehensively investigate the relationship between FGFR4 G388R, V10I variants and cancer risk, we conducted the present analysis based on all eligible studies and used online databases and immunohistochemical staining (IHS) to assess the expression of FGFR4 further." (PMID 33446698, 2021). "Aberrant FGFR4 signaling is implicated in tumorigenesis of several cancers." (PMID 33182650, 2020). "Therefore, this updated meta-analysis including more eligible studies was performed to evaluate the impact of FGFR4 polymorphisms on cancer susceptibility." (PMID 33017009, 2020). "Activation of FGF19/FGFR4 signaling is closely associated with cancer development and progression." (PMID 33066597, 2020). "Mutated FGFR4 was found to induce local growth and enhance metastasis in these cancers." (PMID 32111983, 2020). "For FGFR4 rs351855 polymorphism, the findings from 34 studies including 10407 cases and 12382 controls did not support an association between this polymorphism and overall cancer susceptibility." (PMID 33017009, 2020). "Several studies have focused on the association between FGFR4 polymorphisms and cancer development." (PMID 33017009, 2020). "Furthermore, activation of FGF19/FGFR4 signaling is closely associated with cancer development and progression." (PMID 33066597, 2020). "Considering these indications, further linking FGFR4 to apoptosis evasion in human tumors and 3D cultures, we next systematically interrogated the association of FGFR4 activity with drug sensitivity and resistance, targeting clinically actionable vulnerabilities of cancer cells." (PMID 30903103, 2019). "Aberrant FGFR4 signaling pathways, resulting from gene mutation, amplification or overexpression, play an important role in the proliferation, survival and metastasis of a variety of cancer cells." (PMID 27618313, 2016). "Therefore, the prognostic role of the FGFR4 Arg388 polymorphism may also be different among different types of cancer." (PMID 34737965, 2021). "Therefore, the SNP may increase cancer risk through other mechanisms, including altering FGFR4′s ligand affinity, degradation, or its capacity to interact with downstream effectors." (PMID 28445975, 2017). "Fibroblast growth factor 19 (FGF19) and its receptor, FGFR4, present a significant axis in cancer biology, particularly in HCC." (PMID 41503573, 2026). "Given the involvement of FGFR4, the diversity of downstream pathways and outcomes necessitates cancer-specific strategies." (PMID 41328353, 2026). "The binding and phosphorylation mechanism of FGF19 with FGFR4 is similar in various types of cancer, including HCC and BC." (PMID 41328353, 2026). "These research results not only reveal the critical role of the FGF19/FGFR4 signaling pathway in cancer drug resistance but also provide a theoretical basis for the development of more effective targeted therapeutic strategies." (PMID 41328353, 2026). "The suppression of FGFR4 at low deuterium supports the potential anti-cancer effects of DDW by inhibiting oncogenic signaling." (PMID 41303451, 2025). "FGFR4-overexpressing cancer cells promoted CAF abundance and activation in vivo, while also inducing the differentiation of normal fibroblasts into CAFs via their secretome." (PMID 40447617, 2025). "FGFR4 is a known regulator of metastasis in other cancer types and can be therapeutically targeted, though it’s role in PDAC metastasis is uncharacterized." (PMID 40731412, 2025). "FGFR4 serves an oncogenic function in several cancer types and promotes metastatic spread in other gastrointestinal cancers." (PMID 40731412, 2025).
cancer (continued). "FGFR4-overexpressing cancer cells induced CAF differentiation/activation and exhibited higher concentrations of CXCL10 than control cells." (PMID 40447617, 2025). "Compared to the control cell line,eFGF1-161Tb showed much higher uptake and significantlyenhanced cytotoxicity on both FGFR1 and FGFR4 overexpressing celllines, which suggests that eFGF1-161Tb is a promising candidatefor targeted cancer therapy." (PMID 39989790, 2025). "Among them, FGFR4 has been reported to promote cancer cell proliferation, invasion, survival, and chemoresistance in multiple cancer types." (PMID 41213916, 2025). "FGFR4 enhances metastasis, angiogenesis, chemoresistance, and cancer cell stemness across various digestive system tumors." (PMID 39857726, 2025). "The number of α-SMA-positive cells significantly increased in TME, suggesting that FGFR4 overexpression in cancer cells enhances CAF abundance in TME." (PMID 40447617, 2025). "We found that a small number of genes (e.g., RET, RECQL4, CUX1, FGFR4, PIK3R1, FGFR3, and GNAS) had some co-occurring variants per patient in different cancer types." (PMID 38637555, 2024). "A significant association of FGFR4 expression with the FGF19 ligand has been observed in cancer progression and metastasis, making it a promising therapeutic target against cancer." (PMID 38540215, 2024). "In several cancer subsets, induction of oncogenic STAT3 associates with increased expression of FGFR4, a member of a tyrosine kinase family of FGFRs involved in cell growth, differentiation and migration." (PMID 37945798, 2024). "Compared with FGFR4-Gly388 patients, FGFR4-Arg388 patients were more likely to have a higher cancer stage, poorer survival, and significantly higher levels of wave proteins (p = 0.025) and p-STAT3 (p = 0.009)." (PMID 39309860, 2024). "The LIF/STAT3/FGFR4 axis can serve as survival mechanism to promote the growth of neoplastic cells and development of cancer cells chemoresistance." (PMID 37945798, 2024). "FGFR4 p.G388R (rs351855) has been reported to prompt progression and affect prognosis of several cancers including CRC." (PMID 38650006, 2024). "Of the four FGFRs (FGFR1–4), the function of the FGFR4 signaling pathway in cancer is the least characterized, although it is known to play an important role in hepatobiliary physiology and tumor progression." (PMID 36622048, 2023). "Overexpression of FGFR4 and its ligand FGF19, as well as somatic mutations, have been identified in multiple cancers." (PMID 37789421, 2023). "In the present study, we determined that Roblitinib, a representative FGFR4 inhibitor, exerted anti-cancer effects in HCC cells, and these effects can be enhanced by EZH2 inhibitor CPI-169." (PMID 37085881, 2023). "Previous reports indicate that FGFR4 is overexpressed in cancers such as breast cancer, rhabdomyosarcoma, and ovarian cancer." (PMID 36803783, 2023). "We estimated the ratio of FGFR4 expression between the cancer region and normal renal epithelium areas (T/N ratio) as a quantitative index of FGFR4 expression, with an average FGFR4 T/N ratio of 1.786 and a standard deviation of 0.76." (PMID 36803783, 2023). "Given that FGFR4 inhibitor treatment can prevent the growth of several types of cancer cells, we further evaluated the effect of FGFR4 inhibition in conjunction with METTL16 inhibition on CCA cell growth." (PMID 37817227, 2023). "Since, in CRCs, FGFR4 mediates cancer progression via phosphorylation of STAT3, we assessed its phosphorylation status at the Y705 site in CRC cells after TRIP13 shRNA knockdown and treatment with DCZ0415." (PMID 35194944, 2022). "In contrast to the normal production and action of FGF19 as an endocrine hormone, FGF19 is overexpressed and co-expressed with FGFR4 in various cancers of liver, breast, lung, bladder, head, and neck, indicating FGF19 as a driver oncogene." (PMID 35296193, 2022).
cancer (continued). "Our study will provide a novel research direction for the next generation of FGFR4 inhibitors to treat HCC or other FGFR4-dependent cancers." (PMID 36697897, 2022). "Another study has shown that the G388R in the protein kinase domain on FGFR4 has been proven to increase the potential of promoting cancer cells." (PMID 35888106, 2022). "As a key node in the YAP/Hippo pathway, MST1/2 are phosphorylated in an FGFR4 kinase activity-dependent manner, resulting in the proliferation and metastasis of cancer cells." (PMID 35562334, 2022). "In cancers, the hyper‐activation of FGFR4 signalling is a common alteration leading to the activation of various intracellular pathways, including GSK3β/β‐catenin/E‐cadherin, FGFR4–GSK3b–Nrf2 signalling and PI3K‐AKT." (PMID 35194944, 2022). "Substantial studies have shown that the stimulation of the FGFR4 pathway endows cancer with the capacity to resist cancer therapies and chemotherapies." (PMID 33981224, 2021). "It has been shown that some mutations in N535 and V550 kinase domain residues of the FGFR4 located result in the more stable activity of the FGF/FGFR4 pathway in different types of cancers." (PMID 34400727, 2021). "Abnormal FGFR4 production explains these cancer formations, and therefore, this receptor has emerged as a potential target for inhibiting cancer development." (PMID 33981224, 2021). "This evidence make combination of FGFR4 inhibitors and immune therapy a feasible method for cancer patients." (PMID 34576070, 2021). "Many researchers also examined the relationship between the FGFR4 gene SNP and its pathological or prognostic roles among diverse cancer types." (PMID 34737965, 2021). "The Kaplan–Meier survival analysis showed that the expression of FGFR4 was closely related to the prognosis of cancer patients (P-value = 0.0339)." (PMID 33407583, 2021). "6LF has the potential to be a targeted treatment option for personalized medicine in cancer patients who suffer from FGFR4 V550L drug resistance." (PMID 34400727, 2021). "The irregular expression of the FGFR4 pathway may be induced by gene amplification, posttranscriptional errors, FGFR4 mutations, translocations, isoform switching, alternative splicing of FGFR4, and overexpression of specific ligands in cancer or stromal cells." (PMID 33981224, 2021). "Fibroblast growth factor receptor 4 (FGFR4) is a receptor tyrosine kinase that has been shown to play a key role in cancer development and prognosis via the activation of its downstream oncogenic signaling pathways." (PMID 34071523, 2021). "Among the FGFR family members, the role of FGFR4 in cancer has been expounded on by only a few studies." (PMID 33981224, 2021). "Some of them, mainly reported in models of cancer cell lines or transgenic mice, indicate that the blockage of FGFR4 dimerization with antibodies or the use of FGFR4 knock-out mice completely prevented hepatocarcinogenesis." (PMID 34200439, 2021). "The blockade of FGF19/FGFR4 signaling would have great potential in improving the efficacy of melatonin supplements in cancer treatment." (PMID 33691750, 2021). "Herein, we reviewed various inhibitors of FGFR4 in the cancer microenvironment, including immune evasion, paracrine signaling, and angiogenesis." (PMID 33981224, 2021). "On the other hand, genetic instability of SNP allele rs351855-A in fibroblast growth factor receptor 4 (FGFR4) enhances STAT3 cascade and shapes TME in multiple cancer types, attributed to STAT3-pY705 elevation." (PMID 33957948, 2021). "Like other FGFR family members, aberrant FGFR4 activation is closely related to cancer progression and resistance to anti-cancer therapy." (PMID 33407583, 2021). "FGFR4 overexpression increased Bcl-x expression at the mRNA and protein level through the MAPK cascade, implying that FGFR4 inhibitors (e.g., opposing antibodies) combined with chemotherapeutic drugs should be used for treating FGFR4-overexpressing cancers." (PMID 33981224, 2021).
cancer (continued). "Moreover, FGFR4 deficiencies could regulate the TIICs and trigger a therapeutic immune response to tumors by the activation of the antigen presentation process and anti-cancer cellular immunity in NSCLC." (PMID 33407583, 2021). "Although PD173074 is always used as FGFR1 inhibitor, it can also block cancer cell proliferation via the FGFR4 signaling pathway." (PMID 32555680, 2020). "Blocking FGFR4 significantly suppresses the cancer and indicates that FGFR4 is a potential target for the cancer treatment." (PMID 33017009, 2020). "Accumulating evidence indicates that FGFR4 plays a critical role in cancer progression and metastasis, particularly in those cancer patients who have FGF19 amplification." (PMID 32154250, 2020). "Since active FGF19-FGFR4 signaling acts as an oncogenic pathway in certain types of cancer, the development and therapeutic evaluation of FGFR4-specific inhibitors in cancer patients is a topic of significant interest." (PMID 32154250, 2020). "As for the receptors of the FGF ligands, four distinct FGF receptors (FGFRs), FGFR1 (Flg), FGFR2 (K-sam), FGFR3, and FGFR4 exist, and if deregulated can function as oncogenes to drive specific cancer types including GC." (PMID 33178597, 2020). "In the past few years, there were few epidemiological analysis and meta-analysis focusing on FGFR4 in uterine leiomyomata, hip bone geometry, and all types of cancer." (PMID 33017009, 2020). "Compared to the other three FGFR family members, the function of the FGFR4 signaling pathway in cancer is less well-characterized." (PMID 32154250, 2020). "We selected novel FGFR4-sdAb with high specificity and nano- to picomolar affinities for FGFR4 which have the potential to enable multiple FGFR4-targeted cancer therapy approaches." (PMID 33182650, 2020). "The FGF19/FGFR4 signaling is known to promote invasion and metastasis in several different types of cancer." (PMID 33066597, 2020). "We explored four SNPs of FGFR4, namely rs2011077, rs351855, rs7708357, and rs1966265, to examine the pathophysiological effects on tumorigenesis of several cancers." (PMID 32781755, 2020). "Further, we examined the possibility of enhancing the therapeutic efficiency of FGFR4 inhibitors in cancer patients." (PMID 32154250, 2020). "Increasing evidence indicates that upregulation of FGFR4 expression levels participate in tumorigenesis and cancer progression; thus, FGFR4 has been proven as a therapeutic target for several cancers." (PMID 32781755, 2020). "Gaining these insights will improve our comprehensive understanding of the role of FGFR4 in cancer development and treatment." (PMID 30634399, 2019). "Recently, elevated FGFR4 has been tightly correlated with cancer development and progression, making it an attractive target to develop novel and effective anticancer therapeutics." (PMID 30634399, 2019). "And if so, would it offer increased efficacy in combination with targeting HER2, AKT/mTOR, and/or mitochondrial apoptosis pathways in this cancer subset, or in other FGFR4-overexpressing cancers?" (PMID 30903103, 2019). "FGFR4 gene belongs to the fibroblast growth factor receptor family, and the activation of FGFR4 can promote cell growth and angiogenesis in cancer." (PMID 32038722, 2019). "Whole-genome analyses of patient samples have revealed that the number of FGFR mutations and amplifications are generally very low in GBM (FGFR1: 51/3068 samples, FGFR2: 12/2662; FGFR3: 16/2887; FGFR4: 9/2456; cancer.sanger.ac.uk;)." (PMID 31337028, 2019). "Fibroblast growth factor receptor 4 (FGFR4) plays a prominent role in cell proliferation and cancer progression." (PMID 31878098, 2019). "This coupled with specific FGFR4 induction in certain cancers, along with structural differences and drug selectivity relative to other FGFRs, supports the efficacy of FGFR4 as a therapeutic intervention." (PMID 30903103, 2019).